RAD50 (RAD50 double strand break repair protein)
Diseases named in the same sentence as RAD50 in open-access papers (continued):
Sharing a sentence is not in itself a finding about the gene and the disease.
breast cancer (continued). "For example six SEREX antigens identified in serum from breast cancer patients (RAD50, PARD3, SPP1, SAP30BP, NY-BR-62, and NY-CO-58) could identify breast cancer patients from healthy donors with 70% sensitivity and 91% specificity." (PMID 33976232, 2021). "Other genes: Pathogenic variants in BRIP1, RAD51C, RAD50, NBN, STK11, and RECQL may also confer some level of breast cancer risk." (PMID 34439109, 2021). "A RAD50 687delT mutation causes a frameshift to a stop codon, L234Stop, and was associated with increased breast cancer risk in a Finnish population, but this mutation was not seen in other Nordic populations." (PMID 32668560, 2020). "In addition, we also analyzed HERVs that were associated, by localization, with breast cancer development genes (BRCA1, CCND1, ATM, NBS1/NBN, RAD50, KRAS, PI3K/PIK3CA)." (PMID 33194615, 2020). "Through pair-wise and block-wise interactive OS analyses on SNPs of INPP4B and RAD50, we identified two disease-associating blocks, each containing five SNPs (INPP4B) and two SNPs (RAD50), respectively, which synergistically affect breast cancer clinical outcome." (PMID 31872854, 2020). "Similarly, as novel breast cancer susceptibility genes, we found AKT1, ESR2, and RAD50 as the top genes." (PMID 33376724, 2020). "In the most recent studies, the RAD50 gene demonstrated a low OR for breast cancer." (PMID 33134171, 2020). "In breast cancer cells, RAD50 silencing sensitizes cells to DNA damaging agents." (PMID 31767017, 2019). "In BRCA1/2-negatice breast cancer patients, although RAD50 pathologic germline mutations poses no increased risk of cancer, it is nevertheless associated with unfavorable survival." (PMID 31767017, 2019). "We also demonstrated that RAD50 gene mutations are not a risk factor of familial and sporadic breast cancer in the Polish population." (PMID 29678143, 2018). "MRE11A is part of the DNA double-strand break repair MRE11/RAD50/NBS1 complex that is required for non-homologous joining of DNA ends which associates with breast cancer risk." (PMID 30370249, 2018). "In our candidate genes, RAD50 has been reported to be hyper-methylated in breast cancer patients." (PMID 28424414, 2017). "The c.687delT RAD50 mutation, not identified in our study, was reported with significantly elevated frequency in breast cancer patients from Finland." (PMID 24079363, 2013). "In total, 11 DNA repair genes (UBE2A, RBBP8,RAD50, FAAP20, RPA3, ENDOV, DDB2, UBE2V2,MRE11, RRM2B, andPARP3) were preserved as prognostic genes to estimate risk score, which was applied to establish the prognostic model and stratified breast cancer patients into two groups with high or low risk." (PMID 36713553, 2022). "When we look at the association of the HR factor RAD50 with deletions in breast cancer, we find a strong negative association indicating that loss of RAD50 promotes mutations whereas the NHEJ factor KU80 shows a strong positive association indicating higher KU80 expression promotes mutation." (PMID 34147942, 2021). "Furthermore, RAD50 depletion also sensitized human breast cancer cells to cisplatin treatment." (PMID 35006434, 2020). "The protein expression of FGF-2, RAD52, RAD50, PBX2, MAP2K2 (MEK2), and S100P was also validated with immunohistochemistry in invasive breast cancer tumor tissues." (PMID 37445737, 2023). "The protein expression of RAD50, RAD52, and PBX2 was confirmed in breast cancer cell lines MCF7, AU565, BT474, and MDA453 and immortalized breast epithelial cell line MCF10A." (PMID 37445737, 2023). "Both RAD50 and RAD52 are functionally involved in DNA repair, and their protein expression was largely correlated with the focal adhesion protein NEDD9 in breast cancer cells." (PMID 37445737, 2023). "The protein expression of RAD52, RAD50, PBX2, MAP2K2 (MEK2), and S100P was also validated with immunohistochemistry in invasive breast cancer tumor tissues." (PMID 37445737, 2023).
breast cancer (continued). "A total of 11 DNA repair genes, namely, UBE2A, RBBP8,RAD50, FAAP20, RPA3, ENDOV, DDB2, UBE2V2,MRE11, RRM2B, andPARP3, were involved in the prognostic model for breast cancer patients." (PMID 36713553, 2022). "RNA-sequencing data were obtained from primary female breast cancer specimens (n = 1080) from the TGCA breast cancer project and was stratified on the basis of quartile expression of MRE11, RAD50 and NBS1 and differentially expressed genes (DEGs) identified." (PMID 34782604, 2021). "We initially tested MRE11, RAD50 and NBS1 protein expression in a panel of breast cancer cell lines [MCF-7 (ER+, luminal A), ZR-75-1 (ER+, luminal B), SKBR3 (HER2+), MDA-MB-231 (triple-negative)]." (PMID 34782604, 2021). "Using whole exome sequencing, we also identified a rare exonic VUS on RAD50 (c.3647C > G, rs1314725075, MAF = 4.061 × 10–06) in a breast cancer patient originating also from the North Eastern Tunisian region." (PMID 33240314, 2020). "We also explored the impact of HERV expression in its neighboring breast cancer development genes (BRCA1, CCND1, NBS1/NBN, RAD50, KRAS, PI3K/PIK3CA) and in long non-coding RNA expression (AC060780.1, also known as RP11-242D8.1)." (PMID 33194615, 2020). "Previously, we reported that HR genes are overexpressed in sphere cultures obtained from cervical cancer cell lines and that RES inhibits the expression of DNA repair genes such as RAD50 and RAD51 in the MCF-7 breast cancer cell line." (PMID 29681946, 2018). "The multivariate logistics regression analysis was applied to evaluate the performance of the panel of 4 genes (RAD50, RTEL, TERC and TRF1) as biomarkers for breast cancer prediction." (PMID 28424414, 2017). "The 4 genes (RAD50, RTEL, TERC and TRF1) showed significant hyper-methylation and lower expression in breast cancer." (PMID 28424414, 2017). "Other molecular variants in the RAD50 gene: p.I94L in exon 3 and p.R224H in exon 5, intronic variant IVS3-1G>A and a nonsense mutation p.Q350X in exon 7 have been observed at a low frequency not allowing to determine whether the variants increased the risk of breast cancer." (PMID 24093751, 2013). "The most significant differences in expression pattern were revealed for RAD50 and LGALS3BP in different histological types of breast cancer and for PABPC4 and FAM50A antigens in immune cells infiltrating breast tumors." (PMID 23181716, 2012). "This pilot study made possible to select 4 antigens LGALS3BP, RAD50, PABPC4, and FAM50A as promising candidates for more comprehensive research as potential molecular markers for breast cancer diagnostics and therapy." (PMID 23181716, 2012). "In current study we analyzed six previously identified medullary breast carcinoma autoantigens including LGALS3BP, RAD50, FAM50A, RBPJ, PABPC4, LRRFIP1 with cancer restricted serological profile in different histological types of breast cancer." (PMID 23181716, 2012). "The most significant differences in expression pattern were revealed for RAD50 and LGALS3BP in cancer cells of different histological types of breast cancer and for PABPC4 and FAM50A antigens in immune cells infiltrating breast tumors." (PMID 23181716, 2012). "The most significant differences were observed for RAD50 and LGALS3BP antigens in different histological types of breast carcinomas." (PMID 23181716, 2012).
breast cancer (continued). "Breast cancer 1 (BRCA1) and breast cancer 2 (BRCA2) play an important role in the HR repair pathway by interacting with other DNA repair proteins such as Fanconi anemia (FA) proteins, ATM, RAD51, PALB2, MRE11A, RAD50, and NBN." (PMID 35785170, 2022). "The expression level of DDB2, RPA3,RAD50, RRM2B, and UBE2A was higher in breast cancer tissues with lymph node metastasis compared with breast cancer tissues without lymph node metastasis, which was estimated by the distribution of their expression level between N0 and N1–N3 stages." (PMID 36713553, 2022). "Our study did not support RAD50, BRIP1 and RAD51C as breast cancer susceptibility genes in the Chinese population, consistent with results from case-control studies in Caucasian women." (PMID 34606182, 2021). "Other PVs were identified in genes that have a less clear association with breast cancer such as: BRIP1, NBN, RAD50 and RECQL, but none of these showed significant associations." (PMID 34439310, 2021). "Both RAD50 and INPP4B are crucial to maintain genomic integrity and prevent tumorigenesis, and co-deletion of both genes commonly co-occurs in many types of cancers including breast cancer." (PMID 31872854, 2020). "MRE11, RAD50, and NBS1 genes were identified as genes with moderate penetrance for breast cancer." (PMID 31767017, 2019). "All 15 breast cancer and 5 non-cancerous tissue samples were positive for the DNA reparation factor RAD50." (PMID 23181716, 2012). "This work is a pilot study, which made possible to select 4 potential breast cancer markers (FAM50, PABC4, RAD50, LGALS3BP) for further studies with larger cohorts of patients with different histological types of breast cancer using automated measurement systems for immunohistochemical analysis." (PMID 23181716, 2012). "Also, no mutations were detected for other described breast cancer‐associated genes (e.g., RAD51, RAD50, p27, ESR1/2, ERBB2, ERBB3, AKT1, CCDN1, FGFR1, MYC, and RB1) in any of the tissues or the CTC cell line." (PMID 32667137, 2020). "By applying the CIPHER-HIT to the subtype analysis of Breast cancer, we found that the prioritized genes can be divided into two sub-modules, one contains the members of the Fanconi anemia gene family, and the other contains a reported protein complex MRE11/RAD50/NBN." (PMID 21599985, 2011). "Within Asia, a South Korean study of 235 patients at high-risk for hereditary breast cancer and were confirmed not to have a BRCA1/2 mutation were tested with massively parallel sequencing, and 3.6% were found to have pathogenic germline mutations in CHEK2, PALB2, MRE11 and RAD50." (PMID 30093976, 2018). "Thus, during this study we described for the first time expression patterns of 6 potential MBC-associated antigens, including LGALS3BP, RAD50, FAM50A, RBPJ, PABPC4, LRRFIP1 in different histological types of breast carcinomas and non-cancerous breast tissues by immunohistochemical analysis." (PMID 23181716, 2012). "Another limitation is that sequence data was unavailable for MRE11, RAD50 or NBS1 in these specific patients and it was not possible to investigate in patients with familial breast cancers." (PMID 34782604, 2021). "Unlike RAD50, MUC1 has not been classified as a driver gene in breast cancer and was therefore not included in further analysis." (PMID 28241424, 2017). "CHEK2 1100delC, RAD50, and NBS1 do not appear to correlate with breast cancer in the Chinese population and should not be considered in genetic testing." (PMID 23318652, 2013).
ovarian carcinoma (37 papers, 2011 to 2025). A malignant neoplasm originating from the surface ovarian epithelium. "In particular, nuclear accumulation of the MRN complex was associated with chemo-resistance in gastric cancer and ovarian cancer, and high expression of RAD50 correlates with radio-resistance in colorectal cancer (CRC) patients." (PMID 37509263, 2023). "BRCA1, a tumor suppressor protein linked to breast and ovarian cancer, interacts with RAD50 in vitro and in vivo and co-localizes with RAD50, MRE11, and NBS1 in irradiation-induced foci." (PMID 36008939, 2022). "In 2020, PARP inhibitors were used for ovarian cancer patients with mutations in 14 HRR genes including RAD50, which provides potential therapeutic targets and options for treating ovarian cancer patients with mutations in HRR mutations." (PMID 36729997, 2022). "In patients with ovarian cancer, instead, variants were identified mainly in the RAD50 and RAD51C genes." (PMID 34299313, 2021). "In the current study we provide evidence that RAD50 deficiency is a predictor of platinum sensitivity in epithelial ovarian cancers." (PMID 35006434, 2020). "Taken together, the data provides evidence for a role for variants in RAD50 and its associated complex in platinum resistance in ovarian cancer cell lines." (PMID 35006434, 2020). "In BRCA wild-type (BRCAwt) ovarian cancer patients, 18% of the patients exhibit RAD50 deletion, and this deletion is associated with significantly better overall survival (OS) and progression-free survival (PFS)." (PMID 31767017, 2019). "The Rad50 gene was proved to be an important pathogenic mutation in ovarian cancer." (PMID 36729997, 2022). "We have also investigated Mre11 and Rad50 variants in ovarian cancer cells." (PMID 33435622, 2021). "RAD50 polymorphisms are also associated with increased risk of breast and ovarian cancer." (PMID 35006434, 2020). "The data including ours provide evidence that RAD50 deficiency is not only a marker of platinum sensitivity but could also predict response to PARP inhibitor therapy in epithelial ovarian cancers." (PMID 35006434, 2020). "RAD50 polymorphisms are associated with increased risk of breast and ovarian cancer." (PMID 35006434, 2020). "Germ-line mutations in RAD50 has been linked to breast and ovarian cancer susceptibility." (PMID 35006434, 2020). "Our previous research also demonstrated that SIC-19, which targets SIK2, affects DNA HR repair and increases the vulnerability of ovarian cancer cells to PARP inhibitors by inhibiting phosphorylation at RAD50-Ser635." (PMID 40612876, 2025). "By directly phosphorylating RAD50 at the Ser635 site in ovarian cancer, SIK2 can influence nuclear microfilament formation and DNA recombination repair, which in turn affects sensitivity to PARP inhibitors." (PMID 40612876, 2025). "In ovarian cancer cells (A4-T), irregular chromosomal segregation also occurred when silencing RAD50 and XRCC5, under conditions of genomic stress." (PMID 37407587, 2023). "Other HRR pathway-related genes (ATM, ATR, CDK12, FANCA, FANCD2 and RAD50) were also found to play an essential role in ovarian cancer pathogenesis." (PMID 36729997, 2022). "In co-immunoprecipitation experiments, in ovarian cancer cell lines, we also observed that Mre11 physically interacted with Nbs1, Rad50, XRCC1 and LIG3 consistently in PEO1 cells." (PMID 35853939, 2022). "The studies of MRN complex (RAD50, MRE11, NBN) mutations and ovarian cancer summarized above are contradictory and are insufficient to determine ovarian cancer risk." (PMID 35159349, 2022). "Here, we have demonstrated a strong positive correlation between Mre11, Rad50 and Nbs1 in clinical ovarian cancer cohorts." (PMID 35853939, 2022). "Overexpression of Rad50 increased the phosphorylation of p65 and decreased total IκBα protein levels while knockdown of Rad50 significantly decreased p‐p65 protein level in ovarian cancer cell lines." (PMID 34734468, 2021).
ovarian carcinoma (continued). "Among the four cases of patients with ovarian cancer, we found a Pathogenic variant in RAD51C, 2 VUSs, respectively in ATM and RAD50 genes, and a Likely-benign variant in STK11." (PMID 34299313, 2021). "Clinicopathological significance of RAD50 protein was evaluated by immunohistochemistry in 331 human ovarian cancers." (PMID 35006434, 2020). "Taken together, the clinical and pre-clinical data provides evidence that RAD50 is a predictor of platinum sensitivity in ovarian cancer." (PMID 35006434, 2020). "In BRCA wild-type ovarian cancers, RAD50 deletion was shown in 18% of tumours and correlated better PFS and OS." (PMID 35006434, 2020). "In ovarian cancer cell lines, following cisplatin therapy, we observed increased nuclear accumulation of RAD50 protein in nuclear extracts in platinum resistant cell lines compared to platinum sensitive cell lines." (PMID 35006434, 2020). "Clinicopathological significance of RAD50 expression was evaluated in clinical cohorts of ovarian cancer at the protein level (n = 331) and at the transcriptomic level (n = 1259)." (PMID 35006434, 2020). "Nevertheless, RAD50 depletion in platinum resistant ovarian cancer cells increased cisplatin cytotoxicity." (PMID 35006434, 2020). "For further validation, we investigated RAD50 mRNA expression in a publicly available online gene expression database of 1259 ovarian cancer cases treated with platinum therapy." (PMID 35006434, 2020). "In contrast, low RAD50 expression was observed in low-grade epithelial ovarian cancer in another study." (PMID 35006434, 2020). "For example, NBN and RAD50 were once considered to be associated with increased breast/ovarian cancer risk, but are no longer thought to be associated with cancer risk." (PMID 35626031, 2022). "HO-8910 ovarian cancer cells treated with 17-AAG had significantly reduced levels of RAD50." (PMID 36008939, 2022). "Furthermore, according to research, RAD50 double strand break repair protein-mediated NF-κB pathway activation in ovarian cancer is dependent on CARD9, and interfering with CARD9 reduces ovarian cancer cell migration." (PMID 36443670, 2022). "Interestingly, overexpression of Rad50 increased the phosphorylation of p65 and decreased total IκBα protein levels while knockdown of Rad50 significantly decreased p‐p65 protein level in ovarian cancer cell lines." (PMID 34734468, 2021). "To this end, we performed immunoprecipitation (IP)–western blot to test whether Rad50 can interact with CARD9 in ovarian cancer cells." (PMID 34734468, 2021). "Therefore, we identified CARD9 as an interacting protein of Rad50 in ovarian cancer cells and Rad50‐mediated activation of NF‐κB pathway is CARD9 dependent." (PMID 34734468, 2021). "Our findings in this study demonstrated that Rad50 has oncogenic properties in ovarian cancer." (PMID 34734468, 2021). "We proposed that Rad50 may also activate NF‐κB pathway via the interaction with CARD9 in ovarian cancer cells." (PMID 34734468, 2021). "In summary, our findings showed that Rad50 exhibits oncogenic property in ovarian cancer." (PMID 34734468, 2021). "Our data suggest that Rad50 could be a prognostic biomarker and a potential therapeutic target for ovarian cancer." (PMID 34734468, 2021). "Strikingly, Rad50 was increased in olaparib‐resistant ovarian cancer cells in GSE 117765 data." (PMID 34734468, 2021). "Moreover, we identified CARD9 as an interacting protein of Rad50 in ovarian cancer cells and the activation of NF‐κB pathway by Rad50 is CARD9 dependent." (PMID 34734468, 2021). "To verify whether Rad50‐mediated activation of NF‐κB pathway is CARD9 dependent, we knocked down CARD9 in Rad50‐overexpressed ovarian cancer cell lines and found that knockdown of CARD9 significantly reversed Rad50‐induced migration activities." (PMID 34734468, 2021). "Furthermore, we verified CARD9 as a specific interacting protein of Rad50 in ovarian cancer cells and Rad50‐mediated activation of NF‐κB pathway is CARD9 dependent." (PMID 34734468, 2021).